MDGA2 (MAM domain containing glycosylphosphatidylinositol anchor 2)
Description:
May be involved in cell-cell interactions.
Synonyms: MAMDC1; DEE122; c14_5286
Tractability: Antibody: UniProt places it where antibodies can reach, with high confidence; its Gene Ontology location is reachable by antibodies, with high confidence; UniProt predicts a signal peptide or a membrane-spanning region. PROTAC: ubiquitination databases record sites on it; its protein half-life has been measured.
Safety:
Unwanted effects reported when the protein is acted on. In parentheses: how it was acted on, where the effect was seen, and who reports it.
sexual dysfunction (source: ClinPGx)
Gene: Protein-coding gene on chromosome 14 (46,840,092 to 47,675,605, reverse strand). Ensembl gene ENSG00000139915.
Subcellular location: Cell membrane
Pathways (Reactome):
Metabolism of proteins: Post-translational modification: synthesis of GPI-anchored proteins
Gene Ontology:
Biological process: nervous system development; spinal cord motor neuron differentiation
Cellular component: extracellular region; plasma membrane; membrane
Genetic constraint (gnomAD): Loss-of-function variants: 24 observed, 93.36 expected, observed/expected ratio (o/e) 0.26, 90% interval 0.19 to 0.36. The upper end of that interval is the gene's LOEUF score, 0.36, which puts it in group 1 of 6, group 1 being the genes least tolerant of losing a copy. Missense variants: 873 observed, 1,053.9 expected, observed/expected ratio (o/e) 0.83, 90% interval 0.78 to 0.88. Synonymous variants: 371 observed, 367.85 expected, observed/expected ratio (o/e) 1.01, 90% interval 0.93 to 1.1.
Homologues: Orthologues: chimpanzee MDGA2 (99% identical), dog MDGA2 (98% identical), pig MDGA2 (98% identical), mouse Mdga2 (97% identical), macaque MDGA2 (93% identical), rabbit MDGA2 (93% identical), rat Mdga2 (92% identical), guinea pig MDGA2 (90% identical), tropical clawed frog mdga2 (80% identical), zebrafish mdga2a (71% identical). Paralogues in human: MDGA1 (49% identical), MALRD1 (16% identical), MAMDC4 (14% identical), MAMDC2 (13% identical).
Diseases named in the same sentence as MDGA2 in open-access papers:
MDGA2 is named in the same sentence as 29 diseases in open-access papers, as found by Europe PMC text mining. Sharing a sentence is not in itself a finding about the gene and the disease. The quoted sentences say what the papers report.
gastric cancer (6 papers, 2017 to 2025). A primary or metastatic malignant neoplasm involving the stomach. "MDGA2 is a tumour suppressor for gastric cancer and hypermethylation of this gene has been associated with gastric cancer prognosis." (PMID 40506516, 2025). "MDGA2 is a tumor suppressor in gastric carcinogenesis, and its hypermethylation is an independent prognostic factor in gastric cancer patients." (PMID 38576019, 2024). "Multivariate analysis also demonstrated that hypermethylation of MDGA2 predicted shortened survival in patients with gastric cancer." (PMID 32489454, 2020). "Wang and colleagues collected samples from 218 patients with gastric cancer and found a methylation of the promoter of MDGA2 (MAM domain containing glycosylphosphatidylinositol) anchored in cancer samples." (PMID 32489454, 2020). "MDGA2/MAMDC1 acts as an antitumor molecule in gastric cancer 45; however, the role of MAMDC2 in cancer, if any, has yet to be elucidated." (PMID 29030909, 2017). "Notably, MAM Domain Containing Glycosylphosphatidylinositol Anchor 2 (MDGA2) also showed the same differential expression but was only studied in gastric cancer and keratin 8 (KRT8), less expressed in proliferating BC cells, was also present in this group." (PMID 40124331, 2025).
autism (5 papers, 2015 to 2025). Persistent deficits in social interaction and communication and interaction as well as a markedly restricted repertoire of activity and interest as well as repetitive patterns of behavior. "Although our study identified Mdga1 while literature more strongly links Mdga2 to autism, both genes belong to the same MDGA family, which are known critical regulators of synaptic development and cortical circuit formation." (PMID 41331623, 2025). "Although some ASD mouse models exhibit a reduced E/I ratio, such as mice with autism-associated mutations in NRXNs or SHANKs, an enhanced E/I ratio can also be observed in many other ASD mouse models, such as TSC1-, MDGA2-, FMRP-, or CUL3-deficient mice." (PMID 34848499, 2022). "This puts MDGA2 in line with other neuronal cell adhesion molecules of the immunoglobulin family, such as contactins, NRCAM, CADM1 and LRFN5 that are implicated in axon migration and guidance and were associated with autism." (PMID 25572423, 2015). "Moreover, we found that in consistent with a previous study, Mdga2 +/− mice displayed autism-like behaviors including impaired nest building ability, increased repetitive self-grooming behavior, and deficits in social affiliation, sociability, and social novelty." (PMID 40168357, 2025).
autism spectrum disorder (5 papers, 2009 to 2025). A spectrum of developmental disorders that includes autism, and Asperger syndrome. "Rationale: Mutations in the synaptic protein MAM domain containing glycosylphosphatidylinositol anchor 2 (MDGA2) have been associated with autism spectrum disorder (ASD)." (PMID 39816685, 2025). "MDGA2 mutations are associated with autism spectrum disorder (ASD) but the underlying mechanisms are poorly understood." (PMID 40168357, 2025). "Memprin/A5/mu (MAM) domain containing glycosylphosphatidylinositol anchor 2 (MDGA2) is an excitatory synaptic suppressor and its mutations have been associated with autism spectrum disorder (ASD)." (PMID 40168357, 2025). "Interestingly, rare deletions in the MDGA2 gene were recently correlated with autism spectrum disorders (ASD)." (PMID 25572423, 2015). "Moreover, in accordance with a role of Mdga2 in cellular migration during brain development, previous large-scale human genetic analyses have associated variations in MDGA genes with schizophrenia, bipolar disorder and autism spectrum disorder." (PMID 25162227, 2014).
Anxiety (3 papers, 2024 to 2025). Intense feelings of nervousness, tension, or panic often arise in response to interpersonal stresses. "In the present study, we used an open field task to test whether this anxiety phenotype is modulated in Nlgn2/MDGA1 dKO or Nlgn2 KO/MDGA2 Het mice." (PMID 39284869, 2024). "We show that loss of MDGA1 expression, but not heterozygous deletion of MDGA2, ameliorates the abnormal cytosolic gephyrin aggregation, the reduction in inhibitory synaptic transmission and the exacerbated anxiety-related behaviour characterizing Nlgn2 knockout (KO) mice." (PMID 39284869, 2024). "Taken together, our observations indicate functional interactions between MDGA1 and Nlgn2 KOs, but not between MDGA2 and Nlgn2 KOs, in modulating the neuronal circuits that regulate anxiety-related avoidance behaviors." (PMID 39284869, 2024). "No amelioration of the Nlgn2 KO anxiety phenotype was observed in male or female Nlgn2 KO/MDGA2 Het mice, consistent with the lack of an effect of MDGA2 Het on gephyrin aggregation and GABAergic synaptic transmission." (PMID 39284869, 2024).
schizophrenia (3 papers, 2014 to 2025). A major psychotic disorder characterized by abnormalities in the perception or expression of reality. "We examined expression of known GPI-APs previously associated with schizophrenia, GPC1, NCAM1, MDGA2, and EPHA1." (PMID 30664618, 2019). "To investigate the potential consequences of a deficit in export and/or quality control, we measured cell membrane-associated expression of known GPI-APs that have been previously implicated in schizophrenia, including GPC1, NCAM, MDGA2, and EPHA1, using Triton X-114 phase separation." (PMID 30664618, 2019).
nasopharyngeal carcinoma (2 papers, 2024 to 2025). A carcinoma arising from the nasopharyngeal epithelium. "More recently, MDGA2 has also been postulated as a relevant diagnostic and prognostic biomarker for breast and nasopharyngeal cancers." (PMID 40506516, 2025). "However, advanced-stage nasopharyngeal carcinoma patients exhibited higher MDGA2 expression levels compared to those in the early stage, aligning with our results." (PMID 38576019, 2024).
bladder tumors (1 paper, 2023). "From the identified signature gene set, MDGA2, GNLY, DLX1, and DSC1 were selected for expression analysis in bladder tumors and matching blood samples of 10 BLCA patients." (PMID 37876438, 2023).
bovine tuberculosis (1 paper, 2024). "Other genes found in the present study related to immunity and adaptation in literature were DNAJC17 (heat tolerance in Zebu cattle), GCHFR, MDGA2 (heat stress in cows), FOXF1, NKG7 (bovine tuberculosis response), and SIGLEC10." (PMID 39766784, 2024).
Cognitive impairment (1 paper, 2025). Abnormal cognition is characterized by deficits in thinking, reasoning, or remembering. "Whether other mechanisms responsible for repetitive behavior and cognitive impairment caused by MDGA2 deficiency exist deserves further scrutiny." (PMID 40168357, 2025). "Herein, we found that Mdga2-deficient mice exhibited ASD-like behaviors including social deficits, repetitive behavior, and cognitive impairment." (PMID 40168357, 2025).
developmental and epileptic encephalopathy (1 paper, 2026). An epilepsy associated with developmental impairment that may be due to either the underlying etiology or the superimposed epileptic activity, or both. "Through exome sequencing, we identified seven distinct homozygous loss-of-function variants in MDGA2 in nine individuals from seven consanguineous families, all presenting with developmental and epileptic encephalopathy (DEE)." (PMID 41570816, 2026).
Intellectual disability (1 paper, 2025). "Since MDGA2 is a target of the AF4/AFF member 3 (LAF4/AFF3) transcription factor and its overexpression partially rescues phenotypes caused by LAF4/AFF3 deficiency, MDGA2 may also mediate LAF4/AFF3 deletion-caused neurodevelopmental defects and intellectual disability." (PMID 40168357, 2025).
tumor (5 papers, 2021 to 2025). "Of special importance is the discovery of two genes MDGA2 and STARD3 for which significant associations with many other tumour types have been previously found." (PMID 40506516, 2025). "The expression of the four target genes (MDGA2, DLX1, DSC1, and GNLY) was investigated in tumor tissues and paired blood samples from 10 BLCA patients who were enrolled in the current study." (PMID 37876438, 2023).
cancer (4 papers, 2014 to 2022). A tumor composed of atypical neoplastic, often pleomorphic cells that invade other tissues. "We found that except LY6K and MDGA2, all other hub genes were differentially expressed between PCa tissues and para-carcinoma tissues." (PMID 35780240, 2022).
neurological disorders (1 paper, 2019). "Additionally, genes previously associated with neurological disorders were similarly up regulated, such as Mdga2, Clu, Epha3, Chl1, Cntn4, Cdh23, and Pard3b." (PMID 30628890, 2019).
MDGA2 also shares sentences with these, for which no sentence is quoted: depression (2 papers); bipolar disorder (1); breast adenocarcinoma (1); colon carcinoma (1); cutaneous squamous cell carcinoma (1); epidermoid carcinoma (1); Epileptic encephalopathy (1); insomnia (1); monocytic leukemia (1); neuroblastoma (1); psychiatric disorder (1); retina degeneration (1); Retinal dystrophy (1); sexual dysfunction (1); systemic lupus erythematosus (1).